SGPL1 (sphingosine-1-phosphate lyase 1)
Diseases named in the same sentence as SGPL1 in open-access papers (continued):
Sharing a sentence is not in itself a finding about the gene and the disease.
tumor (continued). "Finally, in SGPL1-downregulated cells, tumor cell apoptosis was induced, and the effect of hnRNP siRNA was negated, clearly indicating that hnRNP H1 function was mediated by SGPL1." (PMID 32630435, 2020). "SGPL1 activity is known to support the overcome of chemotherapeutic drug resistance, increase the sensitivity of cells to stress and is ascribed to display a tumor suppressing and anti-oncogenic behavior." (PMID 31455837, 2020). "SGPL1 expression was also downregulated in RCC tumor samples, which supports our narrative." (PMID 32630814, 2020). "Besides, SGPL1, a protein promoting cell apoptosis, was found to be expressed in the adrenal cortex, and down-regulated in tumor." (PMID 32175564, 2020). "Oppositely, SGPL1 knockout in immune cell compartment leads to massive immune cell infiltration within colon tissue resulting in tissue damage and pathological crypt remodeling that induced delayed tumor formation." (PMID 32456134, 2020). "Tumor cells benefit from this circumstance, either by overexpressing the S1P synthesizing kinases (Sphk1, 2) or by repressing of the irreversible degrading lyase (SGPL1)." (PMID 29718989, 2018). "We then asked whether Sgpl1-edited BMDMs promote anti-tumor immunity in vivo." (PMID 37388918, 2023). "Thus, it might be that depletion of SGPL1 has a tumor suppressive effect in already established tumor cells." (PMID 34073605, 2021). "However, supposedly, CSCs are able to ‘decide’ not to insist on their self-renewing under the SGPL1 knockout mutation to avoid the inescapable process of transferring the mutation into differentiated cells and accomplish potential tumor development." (PMID 34073605, 2021). "Thus, SGPL1 depletion in colon tissue cell compartment and intracellular S1P signaling result in fast growth of epithelial-driven tumors that facilitate specific immune microenvironment enabling further tumor growth." (PMID 32456134, 2020). "Therefore, low SGPL1 levels can be expected in RMA cells because it is well known that the loss of SGPL1 enhances the emergence for malignancy and tumor cell resistance to chemotherapeutic drugs including cisplatin and daunorubicin, which were used in RMS treatment." (PMID 31455837, 2020). "Mice lacking SGPL1 in intestinal epithelial cells showed enhanced S1P levels and tumor growth, accompanied by increased STAT3 activation and inflammatory cytokine levels, which were inhibited when colonic SGPL1 levels were increased in WT mice." (PMID 35163211, 2022). "Of particular interest, Sgpl1 and Sgpp1, key enzymes involved in the metabolism of S1P, were significantly downregulated across all hepatic cells in the HCC group but increased in hepatocytes, HSCs, ECs, immune cells, and macrophages in the pre-tumor group." (PMID 40057751, 2025). "In contrast, SGPL1 ablation in non-myeloid cells elicited rapid formation of colon tumors accompanied by a tumor-favoring microenvironment." (PMID 35163211, 2022). "Quantification of Ki-67 staining with multi-fluorescent staining in whole colon sections (including tumor) confirmed the absence of Ki-67 positive cells in SGPL1 knockout colon tissue in disease." (PMID 34073605, 2021).
tumor (continued). "Furthermore, the authors of the study found that hnRNPH1 did not influence SGPL1 expression in non-tumorous cells, implying that the hnRNPH1 regulation of target mRNA is rather a tumor-specific phenomenon." (PMID 36611995, 2023). "In contrast to SGPL1, data on S1P phosphatases in experimental tumor models are lacking." (PMID 35163211, 2022). "Therefore, we examined the expression of SPHK1 and SGPL1 in an independent set of tumours (n = 52) and non-malignant control tissues (n = 5) by QPCR." (PMID 27160553, 2016).
infection (11 papers, 2012 to 2025). The state of being infected such as from the introduction of a foreign agent such as serum, vaccine, antigenic substance or organism. "The L. pneumophila effector LpSpl exhibits similarity to eukaryotic SGPL1 in both sequence and activity and has been observed to localize to the mitochondria during infection." (PMID 33251162, 2020). "Not only did the RNAseq experiment confirm our RT-qPCR results (i.e., upregulation of SPHK1 and SPHK2 but also SGPL1 and SGPP1), but also revealed regulation of additional SL metabolism genes upon infection, in addition to a vast array of inflammatory mediators." (PMID 40249190, 2025). "The gene expression levels of S1P synthases (Sphk1, Sphk2) and S1P hydrolases (Sgpl1) in the liver, e-WAT, lung, heart, and aorta of mice were measured by real-time PCR under the infection conditions where a significant increase in plasma S1P concentration was observed." (PMID 34635791, 2021). "Whereas, in PMNs the response to the Ctr infection is characterized by a strong upregulation of SPHK1, at both early (2 h) and late (24 h) infection time points, in M2Φ two counteracting pathways involving upregulation of SPHK1 as well as SGPP1 and SGPL1 likely maintain a steady pool of S1P." (PMID 40249190, 2025).
metabolic disorder (1 paper, 2021). "Sphingosine-1-phosphate lyase insufficiency syndrome (SPLIS) is a rare metabolic disorder caused by inactivating mutations in sphingosine-1-phosphate lyase 1 (SGPL1), which is required for the final step of sphingolipid metabolism." (PMID 33755599, 2021). "Biallelic loss-of-function mutations in sphingosine-1-phosphate lyase 1 (SGPL1) result in sphingosine-1-phosphate lyase insufficiency syndrome (SPLIS), a rare metabolic disorder associated with nonlysosomal sphingolipid storage." (PMID 33755599, 2021).
neurological disease (1 paper, 2017). "Progressive neurological disease was reported in 3 of our patients, but has not been reported in Sgpl1–/– mice." (PMID 28165343, 2017).
skin disorder (1 paper, 2022). Any deviation from the normal structure or function of the skin or subcutaneous tissue that is manifested by a characteristic set of symptoms and signs. "Skin disorders, including the exhibition of scaly hyperchromic plaques, are repetitively observed in SPLIS syndrome, which is caused by SGPL1 deficiency." (PMID 35769463, 2022). "Interestingly, hyperchromic plaque occurred in the mutant mice one month after Imiquimod treatment but not in the controls, which resembled the skin disorder found in Sgpl1 deficient patients." (PMID 35769463, 2022).
SGPL1 also shares sentences with these, for which no sentence is quoted: steroid-resistant nephrotic syndrome (6 papers); nephrotic syndrome type 14 (5); ischemia (4); hepatocellular carcinoma (3); ichthyosis (3); osteopetrosis (3); viral infection (3); Autoimmunity (2); congenital brain malformation (2); embryonal carcinoma (2); genetic disorder (2); lipidosis (2); microcephaly (2); osteoporosis (2); sphingolipidosis (2); African sleeping sickness (1); allergic disease (1); aspergillosis (1); Ataxia (1); atopic dermatitis (1); bowel cancer (1); cardiac arrest (1); cardiac ischemia (1); Cerebellar atrophy (1); Cerebral ischemia (1); chromosomal disorder (1); chronic kidney disease (1); cryptorchidism (1); cystic fibrosis (1); dementia with Lewy bodies (1).
A further 37 diseases each share a sentence with SGPL1 in 1 paper.